GAS6 (growth arrest specific 6)
Diseases named in the same sentence as GAS6 in open-access papers (continued):
Sharing a sentence is not in itself a finding about the gene and the disease.
Alzheimer disease (11 papers, 2011 to 2025). A progressive, neurodegenerative disease characterized by loss of function and death of nerve cells in several areas of the brain leading to loss of cognitive function such as memory and language. "Adeno-associated viral vectors were used to overexpress Gas6 in the APP/PS1 model of Alzheimer’s disease." (PMID 35130912, 2022). "We induced bilateral hippocampal overexpression of Gas6 in the APP/PS1 model of Alzheimer’s disease with stereotactic injections of an adeno-associated virus containing Gas6." (PMID 35130912, 2022). "Gas6 is involved in chemotaxis, mitogenesis, cell growth, and myelination, and has further been shown to rescue cortical neurons from amyloid-β-induced apoptosis, a hallmark of Alzheimer’s disease (AD)." (PMID 29794977, 2018). "First, in the cerebrospinal fluid of patients with Alzheimer’s disease, the protein level of Gas6 was elevated." (PMID 33805625, 2021). "In Alzheimer’s disease patients, the protein level of Gas6 in the cerebrospinal fluid was found to be elevated." (PMID 33805625, 2021). "Novel candidates are associated with neurodegenerative disorders including Alzheimer's disease (VSNL1), prion disease (SCRG1, HSPH1, HSPA5 and CTR9) and age-related degeneration (GAS6 and GNG11)." (PMID 21569303, 2011). "While Gas6 has historically induced anti-inflammatory signatures in the peripheral nervous system, our data suggest an alternative, proinflammatory role in the context of Alzheimer’s disease pathology." (PMID 35130912, 2022). "Also, Gas6 is reported to prevent amyloid beta protein-induced apoptosis of cortical neuron, suggesting its protective role against Alzheimer's disease." (PMID 35174198, 2021). "Additionally, GAS6 is increased in cerebrospinal fluid of Alzheimer’s disease patients compared to controls, and, interestingly, patients with higher cerebrospinal fluid levels of this protein at diagnosis showed a less marked cognitive deterioration over a two-year follow-up." (PMID 39000104, 2024). "Several lines of evidence have supported that Gas6 might play a role in Alzheimer’s disease." (PMID 33805625, 2021). "This work utilizes a novel, chronic method of overexpression of Gas6 and provides evidence for the involvement of TAM receptor signaling in the pathogenesis of Alzheimer’s disease." (PMID 35130912, 2022). "Therefore, we hypothesized that AAV-mediated overexpression of Gas6 would alleviate plaque pathology, reduce neuroinflammation, and improve behavior in the APP/PS1 model of Alzheimer’s disease." (PMID 35130912, 2022). "Thus, we hypothesized that AAV-mediated overexpression of Gas6 in the hippocampus would alleviate plaque pathology, reduce neuroinflammation, and improve behavior in the APP/PS1 murine model of Alzheimer’s disease." (PMID 35130912, 2022).
autoimmune disease (11 papers, 2015 to 2025). A disorder resulting from loss of function or tissue destruction of an organ or multiple organs, arising from humoral or cellular immune responses of the individual to their own tissue constituents. "The immuno-regulatory role of Gas6 has been suggested to be associated with this autoimmune disease via Gas6/TAM systems." (PMID 38890875, 2024). "Consistently, an impairment of the Gas6/TAM system has been associated with the development of autoimmune diseases, as demonstrated by the murine model of triple knock-out for the TAM receptors." (PMID 32454903, 2020). "Gas6 is critical for the maintenance of immune homeostasis and mice deficient in Gas6 or TAM receptors experience severe autoimmune diseases." (PMID 32174917, 2020). "The TAM receptor tyrosine kinases (Tyro3, Axl and Mertk) and their ligands (Gas6 and Pros1) play a pivotal role in the resolution of inflammation and have been associated with chronic inflammatory and autoimmune diseases." (PMID 30729671, 2019). "Axl receptor tyrosine kinase and its ligand Gas6 regulate several biological processes and are involved in both the onset and progression of tumor malignancies and autoimmune diseases." (PMID 38276597, 2024). "Previous studies have also reported that the Gas6/TAM receptor signaling pathway is associated with the development of a variety of diseases, such as autoimmune diseases, tumors, and fibrosis." (PMID 35682869, 2022). "On these bases, Gas6 and its soluble receptors have been proposed as biomarkers in different human conditions, specifically in autoimmune diseases." (PMID 32454903, 2020). "Additionally, investigating whether these mechanisms operate in other inflammatory or autoimmune diseases could broaden the therapeutic scope of the Gas6-AIM axis." (PMID 40034700, 2025). "Gas6/TAM signaling may represent a new class of therapeutic targets in autoimmune disease like SS." (PMID 26445266, 2015). "The Gas6/TAM system has been found to be important in inflammation, hemostasis, cancer, and autoimmune diseases." (PMID 26445266, 2015). "Growth Arrest-Specific 6 (Gas6) and Tyro3, Axl, and MerTK (TAM) receptors are involved in multiple biological processes, including modulation of the immune response, phagocytosis, apoptosis, fibrosis, inflammation, cancer development, and autoimmune disorders." (PMID 39057085, 2024). "Consequently, altered activity/expression of Gas6/TAM components have been discovered in a variety of pathologies, such as inflammation, coagulopathy, cancer, diabetic vascular and renal diseases, and autoimmune disease." (PMID 26445266, 2015).
Autoimmunity (11 papers, 2010 to 2025). The occurrence of an immune reaction against the organism's own cells or tissues. "But also, the downregulation of Gas6 and TAM can cause problems since it is associated with autoimmunity." (PMID 35760058, 2022). "In general, TAM RTKs represent a promising target in autoimmunity as agonistic triggering of these receptors by overexpression of GAS6 has been shown to decrease disease severity in murine models of rheumatoid arthritis and multiple sclerosis." (PMID 34035216, 2021). "Gas6/Axl signaling is a negative regulator of the immune system and inhibition of the Gas6-Axl signaling leads to autoimmunity." (PMID 32174917, 2020). "sAxl is associated with type I IFN stimulation, correlates with Gas6 levels and shows minor associations with SLE activity and autoimmunity." (PMID 24325951, 2013). "It has been suggested that Gas6 is involved in macrophage activation in chronic autoimmunity as an autocrine or paracrine regulatory molecule for monocytes." (PMID 20637106, 2010). "Since mononuclear activation with cytokine production is crucial in the amplification of the autoimmune aggression to myelin and the failure to clear apoptotic cells is widely considered a trigger of autoimmunity, Gas6 may have an important role in this context." (PMID 23781120, 2013). "Further research should investigate the role of gene regulation of Gas6 and TAM in tumor progress and autoimmunity." (PMID 35760058, 2022). "The microRNA34/GAS6–Axl axis may resemble the PDL1/PD1 or CTLA‐4/B7 pathways in the mechanism by which they regulate the balance between immunosuppression (cancer) and immunostimulation (autoimmunity)." (PMID 29315512, 2018).
hepatocellular carcinoma (11 papers, 2016 to 2024). A malignant tumor that arises from hepatocytes. "As Axl and its cleavage product soluble Axl (sAxl) have been described to be elevated in EMT-transformed hepatoma cells, we examined sAxl and Gas6 levels in corresponding supernatants and found a highly elevated release of both in mesenchymal-like HCC cells." (PMID 37746265, 2023). "Studies have shown that Gas6 and Axl are highly expressed in hepatocellular carcinoma (HCC) and breast cancer." (PMID 32432570, 2020). "Recently, it was reported that Gas6-Axl signaling increases TGF-β1 expression in mesenchymal hepatocellular carcinoma (HCC) cells via the activation of c-Jun N-terminal kinase (JNK), which promotes Smad3 function." (PMID 27819283, 2016). "Studies have confirmed that CD248 was overexpressed in CAFs of hepatocellular carcinoma (HCC), which promoted the polarization of tumor-associated macrophages (TAMs) to the M2 phenotype, an inhibitory maker in TME, by regulating growth arrest-specific protein 6 (GAS6)." (PMID 34970489, 2021). "Gas6/Axl signaling has emerged as a driver of hepatocellular carcinoma (HCC) progression, impacting several cellular processes, including the epithelial-to-mesenchymal transition (EMT) and metastasis." (PMID 38673795, 2024).
liver disease (10 papers, 2007 to 2024). "The GAS6/AXL pathway was expressed in the case of underlying liver disease, and its inhibition appeared after the induction of liver regeneration, resulting in immune activation." (PMID 37108648, 2023). "Refractory AXL/GAS‐6 signaling, due to chronic overactivation/stimulation in the context of underlying liver disease, appears to abolish their immediate release following induction of liver regeneration, causing overwhelming immune activation, presumably via intrahepatic immune regulation." (PMID 34951136, 2022). "This dual effect on acute and chronic injury has already been proposed as an explanation for Gas6/TAM actions in the immunopathogenesis of liver disorders, but is probably a valid model for other human organs." (PMID 31614787, 2019). "Several studies have shed light on the involvement of Gas6/TAM system in liver diseases." (PMID 38298195, 2024). "Furthermore, we found that Gas/alb was an accurate biomarker for liver disease severity outperforming sAxl, sAxl/alb, and Gas6, as it was not only increasing with fibrosis stage, but also with CPS, MELD, and HVPG, and was able to non-invasively detect CSPH." (PMID 37532736, 2023). "However, a strong positive correlation between plasma Gas6 levels and urinary Gla residues in patients with liver diseases has been found." (PMID 30934817, 2019). "Second, a deleterious role for Gas6 has been established in kidney and hepatic disease." (PMID 17241453, 2007). "Besides cancer, Gas6/TAMs are also involved in liver diseases." (PMID 39057085, 2024). "In addition, Gas6/alb was highly predictive of liver disease severity (Odds ratios for CPS B/C, MELD ≥ 15, and clinically significant portal hypertension (CSPH) were 16.534, 10.258, and 12.115), and was associated with transplant-free survival (Hazard ratio 1.031)." (PMID 37532736, 2023). "Furthermore, we determined if sAxl and Gas6 are specific for HCC by comparison to patients with HCC-free liver disease with and without cirrhosis, and to healthy volunteers, as well as to cholangiocarcinoma (CCA), and to colorectal liver metastases (CRCLM) (n = 1111)." (PMID 37532736, 2023). "Gas6, sAxl, and sMer median plasma levels were not different according to the extent of cutaneous involvement (limited vs diffuse), sex, disease duration (<5 vs ≥5 years), smoking status, liver disease, and immunosuppressive and vasodilator treatments (p = NS)." (PMID 32454903, 2020).
acute myeloid leukemia (9 papers, 2013 to 2023). Acute myeloid leukemia (AML) is a group of neoplasms arising from precursor cells committed to the myeloid cell-line differentiation. "They showed that acute myeloid leukemia cells induce expression and secretion of Gas6 by BMDSCs, and Gas6 in turn mediates proliferation, survival, and chemo-resistance of the Axl-expressing acute myeloid lymphoma cells." (PMID 28878389, 2017). "It was shown that treatment of AXL-transfected U937 acute myeloid leukaemia cells with recombinant GAS6 resulted in resistance to doxorubicin, VP16, and cisplatin, an effect associated with increased expression of the antiapoptotic molecules Bcl-2 and Twist." (PMID 23878800, 2013). "In addition, aberrant Gas6 secretion promotes acute myeloid leukemia cells growth and chemoresistance." (PMID 32298237, 2020). "Under serum starvation conditions, acute myeloid leukemia (AML) Nomo-1 and Kasumi-1 cells with Gas6 and AXL silenced with two distinct shRNAs showed a two- to three-fold increase in apoptosis." (PMID 37265798, 2023). "Patients with acute myeloid leukemia expressing Gas6, especially those aged ≥60 years, more often fail to achieve a complete remission and have shorter disease-free and overall survive than those without Gas6 expression." (PMID 32298237, 2020).
Cirrhosis (9 papers, 2018 to 2024). A chronic disorder of the liver in which liver tissue becomes scarred and is partially replaced by regenerative nodules and fibrotic tissue resulting in loss of liver function. "For the detection of cirrhosis, Gas6/alb was even superior to FIB-4 and showed similar accuracy as ELFTM test." (PMID 37532736, 2023). "Stimulation with GAS6 significantly decreased AXL expression on primary liver macrophages isolated from either 2 patients with cirrhosis or a pathologic control (NCPH) ex vivo, and co-culturing with LX-2 cells displayed a trend for reduced AXL expression." (PMID 37004869, 2023). "We observed significantly increased numbers of α-SMA+ as well as α-SMA+GAS6+ cells across Child-Pugh stages of cirrhosis, suggesting that GAS6 was produced by aHSCs in the context of disease." (PMID 37004869, 2023). "Patients with elevated GAS‐6 and sAXL levels were found to significantly differ in baseline characteristics and displayed a significantly higher frequency of cirrhosis and elevated liver function/damage parameters." (PMID 34951136, 2022). "In fact, plasma Gas6 concentrations are increased in hepatic cirrhosis and correlate with disease evolution and with liver elastography measures, helping to identify severe complications as oesophageal varices." (PMID 32454903, 2020). "In summary, the reduction of AXL expression on liver macrophages on the evolution of cirrhosis presumably involves different mechanisms, potentially including GAS6-mediated down-regulation of AXL and migration of AXL-expressing monocytic cells to extrahepatic compartments." (PMID 37004869, 2023). "Moreover, we previously showed that patients with cirrhosis had elevated plasma GAS6 levels increasing with severity of the disease." (PMID 37004869, 2023). "There are several evidences of the role of the Gas6/Axl system in the modulation of fibrotic evolution of tissues affected by chronic inflammation; in particular, Gas6 is relevant in the modulation of inflammation and fibrosis of the liver and it marks the evolution to cirrhosis." (PMID 32454903, 2020). "As cirrhosis progresses, the expression of Axl by liver macrophages decreases; this might be the consequence of a down-regulation mediated by Gas6, which is conversely upregulated by HSCs, suggesting that Axl may have a role in regulating hepatic immune homeostasis." (PMID 38298195, 2024). "Thus, we hypothesized that GAS6 released by aHSCs in the context of cirrhosis may lead to AXL down-regulation in resident liver macrophages." (PMID 37004869, 2023). "Thus, patients with advanced fibrosis or cirrhosis exhibit already high levels of sAxl and Gas6." (PMID 37532736, 2023). "GAS6, secreted by activated hepatic stellate cells, decreased AXL on liver macrophages in relation to cirrhosis progression." (PMID 37004869, 2023). "Patients with decompensated cirrhosis (CPS B/C), ESLD (MELD ≥ 15), as well as CSPH (HVPG ≥ 10 mm Hg) had significantly higher levels of sAxl, Gas6, and their albumin ratios." (PMID 37532736, 2023). "Decreased AXL expression on resident liver macrophages in advanced cirrhosis, potentially in response to activated HSC-secreted GAS6, suggests a role for AXL in the regulation of hepatic immune homeostasis." (PMID 37004869, 2023). "We also performed immunofluorescent staining on liver biopsies and liver resection tissue from patients with cirrhosis and controls showing AXL, α-SMA, and GAS6 expression." (PMID 37004869, 2023). "We assessed Axl and Gas-6 expression by IHC in archival, paraffin-embedded tissue samples of resected HCC, background cirrhosis and in normal controls (n = 10 in each group)." (PMID 30765873, 2019). "Although Gas6 and Gas6/alb showed high diagnostic accuracy for the detection of HCC in comparison to chronic liver disease patients without cirrhosis (AUC 0.852, 0.868), they failed to discriminate between HCC in cirrhosis versus cirrhosis only." (PMID 37532736, 2023).
Cirrhosis (continued). "The HCC cohort was analyzed in order to evaluate sAxl and Gas6 as diagnostic biomarkers of HCC with and without cirrhosis." (PMID 37532736, 2023). "sAxl and sAxl/alb, as well as Gas6 and Gas6/alb were significantly higher in patients with HCC and underlying cirrhosis as compared to HCC without cirrhosis." (PMID 37532736, 2023). "Circulatory plasma levels of the AXL ligand GAS6 were significantly elevated in cirrhosis compared with HC, independent of the aetiology." (PMID 31822557, 2020). "However, when comparing HCC with underlying liver cirrhosis versus cirrhosis without HCC, sAxl, Gas6 or their albumin ratios exhibited no discriminatory power." (PMID 37532736, 2023). "However, serum Gas6 levels are increased in patients with advanced fibrosis and cirrhosis as well as in HCC patients, suggesting that excess Gas6 is able to overcome the feedback inhibition of sAxl, albeit, these data have to be confirmed in larger patient cohorts." (PMID 30567378, 2018). "Yet, Gas6 and Gas6/alb rather than sAxl and sAxl/alb were higher in HCC without cirrhosis versus healthy controls." (PMID 37532736, 2023).
heart failure (9 papers, 2019 to 2025). Inability of the heart to pump blood at an adequate rate to meet tissue metabolic requirements. "GAS6 administration during the perioperative period enhances MerTK+ cardiac macrophages and angiogenesis, limiting progression to heart failure." (PMID 39195894, 2024). "Klf4, Gas6, and Tsc22d3 showed consistent up-regulation at all timepoints studied post-MI in the adult mouse heart, and in both types of heart failure in human patients." (PMID 36082978, 2023). "Previous results from our group found that Gas6 concentrations were higher in patients with dyspnea related to heart failure or pulmonary/systemic infections when compared to other causes of dyspnea (i.e., pulmonary embolism) or healthy volunteers." (PMID 35203408, 2022). "It was found that patients with heart failure and severe left ventricular remodeling processes have a higher level of sAXL, which indicates the potential role of the GAS6-AXL system in the pathophysiology of these processes." (PMID 32754043, 2020). "Gas6 activation of Axl can induce the ERK signalling cascade, which combined with evidence that Axl levels are elevated in heart failure patients, points to the Gas6-Axl axis as a potential novel therapeutic target in heart failure." (PMID 30980657, 2019). "The significance of the Gas6/AXL complex in heart failure warrants further investigation." (PMID 40933570, 2025). "Hence, the Gas6-Axl interaction might be a therapeutic target in heart failure." (PMID 39684449, 2024). "The mechanism of Gas6-modified MSC therapy for postinfarcted heart failure involves enhanced HIF-1α-driven secretion of four major growth factors (VEGF, bFGF, SDF, and IGF-1) via enhanced Gas6/Axl autocrine prosurvival signalling and paracrine cytoprotective action." (PMID 34510332, 2022).